SLC15A4 (solute carrier family 15 member 4)
Description:
Proton-coupled amino-acid transporter that mediates the transmembrane transport of L-histidine and some di- and tripeptides from inside the lysosome to the cytosol, and plays a key role in innate immune response. Preferably binds to short peptides with a basic residue at the first position and a hydrophobic residue at the second position. Able to transport a variety of di- and tripeptides, including carnosine and some peptidoglycans. Transporter activity is pH-dependent and maximized in the acidic lysosomal environment (By similarity). Involved in the detection of microbial pathogens by toll-like receptors (TLRs) and NOD-like receptors (NLRs), probably by mediating transport of bacterial peptidoglycans across the endolysosomal membrane: catalyzes the transport of certain bacterial peptidoglycans, such as muramyl dipeptide (MDP), the NOD2 ligand, and L-alanyl-gamma-D-glutamyl-meso-2,6-diaminoheptanedioate (tri-DAP), the NOD1 ligand. Required for TLR7, TLR8 and TLR9-mediated type I interferon (IFN-I) productions in plasmacytoid dendritic cells (pDCs). Independently of its transporter activity, also promotes the recruitment of innate immune adapter TASL to endolysosome downstream of TLR7, TLR8 and TLR9: TASL recruitment leads to the specific recruitment and activation of IRF5. Required for isotype class switch recombination to IgG2c isotype in response to TLR9 stimulation (By similarity). Required for mast cell secretory-granule homeostasis by limiting mast cell functions and inflammatory responses (By similarity).
Synonyms: PHT1; PTR4; FP12591
Tractability: Small molecule: a structure with a bound ligand is known. Antibody: UniProt places it where antibodies can reach, with high confidence; its Gene Ontology location is reachable by antibodies, with high confidence; UniProt predicts a signal peptide or a membrane-spanning region. PROTAC: ubiquitination databases record sites on it; its protein half-life has been measured.
Gene: Protein-coding gene on chromosome 12 (128,793,193 to 128,824,035, reverse strand). Ensembl gene ENSG00000139370.
Subcellular location: Lysosome membrane; Endosome membrane; Early endosome membrane
Pathways (Reactome):
Immune System: Neutrophil degranulation; SLC15A4:TASL-dependent IRF5 activation
Transport of small molecules: Proton/oligopeptide cotransporters
Gene Ontology:
Molecular function: dipeptide transmembrane transporter activity; L-histidine transmembrane transporter activity; peptide:proton symporter activity; peptidoglycan transmembrane transporter activity; protein binding; transmembrane transporter activity
Biological process: dipeptide import across plasma membrane; peptidoglycan transport; positive regulation of innate immune response; positive regulation of toll-like receptor 7 signaling pathway; positive regulation of toll-like receptor 8 signaling pathway; positive regulation of toll-like receptor 9 signaling pathway; histidine transport; mast cell homeostasis; oligopeptide transmembrane transport; positive regulation of nucleotide-binding oligomerization domain containing 1 signaling pathway; positive regulation of nucleotide-binding oligomerization domain containing 2 signaling pathway; regulation of isotype switching to IgG isotypes; regulation of nucleotide-binding domain, leucine rich repeat containing receptor signaling pathway; L-histidine transmembrane export from vacuole; oligopeptide transport; proton transmembrane transport; transmembrane transport
Cellular component: endolysosome membrane; lysosomal membrane; early endosome membrane; plasma membrane; specific granule membrane; endosome membrane; membrane
Genetic constraint (gnomAD): Loss-of-function variants: 24 observed, 39.91 expected, observed/expected ratio (o/e) 0.6, 90% interval 0.44 to 0.85. The synonymous counts are far from expectation, so gnomAD's model fits this gene poorly and the ratio says little. Missense variants: 686 observed, 622.14 expected, observed/expected ratio (o/e) 1.1, 90% interval 1.03 to 1.17. Synonymous variants: 336 observed, 268.55 expected, observed/expected ratio (o/e) 1.25, 90% interval 1.14 to 1.37.
Homologues: Orthologues: chimpanzee SLC15A4 (99% identical), macaque SLC15A4 (97% identical), rat Slc15a4 (87% identical), mouse Slc15a4 (86% identical), guinea pig SLC15A4 (86% identical), pig SLC15A4 (86% identical), dog SLC15A4 (78% identical), tropical clawed frog slc15a4 (71% identical), zebrafish slc15a4 (66% identical), rabbit SLC15A4 (59% identical). Paralogues in human: SLC15A3 (50% identical), SLC15A2 (22% identical), SLC15A1 (21% identical), SLC15A5 (19% identical).
Diseases named in the same sentence as SLC15A4 in open-access papers:
SLC15A4 is named in the same sentence as 39 diseases in open-access papers, as found by Europe PMC text mining. Sharing a sentence is not in itself a finding about the gene and the disease. The quoted sentences say what the papers report.
lupus (25 papers, 2016 to 2025). "Variants in SLC15A4 are associated with immune-related diseases, including systemic lupus erythematosus and type 2 diabetes, underscoring its significance in inflammation and innate immunity." (PMID 40869915, 2025). "SLC15A4 encodes a transmembrane transport that has previously been associated with inflammatory autoimmune diseases such as systemic lupus erythematosus from genome-wide association studies." (PMID 37915075, 2023). "With the evident genetic association of the SLC15A4/TASL/IRF5 module with lupus, feeblin represents an encouraging strategy for targeting an etiological mechanism." (PMID 37863876, 2023). "SLC15A4 is one of a number of genes associated with diseases such as systemic lupus erythematosus (SLE) and diabetes, but its physiological roles, apart from the histidine transporter function, have not been examined for many years." (PMID 37781390, 2023). "Genetic variants in SLC15A4 have been associated with increased risk of developing inflammatory diseases like systemic lupus erythematosus." (PMID 36517845, 2022). "Being a proton-dependent peptide/histidine transporter, SLC15A4 protein controls the transport of various molecules from the inside of endosomes to the cytosol and has been associated inter alia with systemic lupus erythematosus." (PMID 35562597, 2022). "Early studies have shown that congenic lupus-predisposed mice lack pDCs because of IRF8 deficiency or SLC15A4 mutation." (PMID 29085361, 2017). "Recent GWASs reported that SLC15A4 is a lupus-associated locus in both the Chinese and Korean populations." (PMID 27362648, 2016). "In addition, SLC15A4 has been identified as a factor associated with susceptibility to systemic lupus erythematosus in mice, and miR-31-5p is a target gene that directly binds to SLC15A4." (PMID 40688069, 2025). "SLC15A4 is a key pathogenic factor in systemic lupus erythematosus (SLE), with dysfunction correlating with disease progression." (PMID 41425581, 2025). "SLC15A4 is preferentially expressed in immune cells and plays critical roles in the pathogenesis of lupus in murine models." (PMID 39671267, 2024). "In summary, slc15a4-/- NZB/W F1 mice were completely protected from lupus even in a situation where IFNα was delivered exogenously, whereas slc15a4+/- NZB/W F1 mice developed the disease in this setting." (PMID 33444326, 2021). "SLC15A4 also participates in the pathogenesis of lupus, which is known as an immune system disorder." (PMID 34168674, 2021). "Our experiments with NZB/W F1 mice validated the importance of slc15a4 for lupus pathogenesis and yielded some surprising results." (PMID 33444326, 2021). "In summary, we demonstrate that the development of lupus is dependent on the presence of slc15a4 in two different murine models." (PMID 33444326, 2021). "First, we studied the consequences of slc15a4 deletion in pristane induced lupus in the C57/BL6 background." (PMID 33444326, 2021). "SLC15A4 is involved in transport of oligopeptides and hydrogen ions out of the lysosome, and knockout of Slc15a4 results in abrogation of TLR7 signaling as well as amelioration of murine lupus." (PMID 31001245, 2019). "GWAS studies have likewise identified slc15a4 as a genetic locus contributing to human lupus in 6 independent studies." (PMID 30262916, 2018). "Interestingly, SLC15A4, IRF5 and TASL are all lupus-associated genes, which strongly suggest that type I IFN production by endosomal TLRs is activated in SLE." (PMID 35812450, 2022). "However, since the expression of adenoviral IFNα is of limited duration, it remains a formal possibility that the role of slc15a4 in lupus is indeed solely to allow for IFNα production." (PMID 33444326, 2021). "SLC15A4-, MyD88-, IRF8-, or IRF5-deficient lupus-prone mice have shown ameliorated lupus symptoms with reduced IFNα protein level in the serum, decreased IFNα transcript level in pDC, downregulation of type I IFN inducible genes, and suppressed activation of both T cells and B cells." (PMID 27034965, 2016).
lupus (continued). "Among the 127 likely pathogenic terms associated with those 68 SLCs (Fig. EV2C), we found systemic lupus erythematosus (SLE) associated with SLC15A2, SLC15A4, and SLC17A3." (PMID 40355757, 2025). "SLC15A4 has been reported in studies of systemic lupus erythematosus (SLE), which is a typical autoimmune disease." (PMID 39671267, 2024). "TASL (TLR adaptor interacting with SLC15A4 on the lysosome), encoded by the TASL (alias CXorf21) gene, is associated with systemic lupus erythematosus (SLE)." (PMID 37296415, 2023). "IRF8 and SLC15A4 may therefore be important targets for therapeutic intervention in lupus." (PMID 29085361, 2017). "We deleted the slc15a4 gene in C57BL/6, NZB, and NZW mice and found that pristane-challenged slc15a4-/- mice in the C57BL/6 background and lupus prone slc15a4-/- NZB/W F1 mice were both completely protected from lupus like disease." (PMID 33444326, 2021). "In order to test the consequences of slc15a4 deletion in a model more reflective of human SLE with severe nephritis, we employed CRISPR technology to introduce deletions into the NZB and NZW strains of lupus prone mice." (PMID 33444326, 2021). "On the contrary, SLC15A4 was found to be required for the production of antibodies in B cells in a mouse model of lupus, and the lack of SLC15A4 in B cells led to reduced production of IgG2a and IgG2c auto-antibodies such as anti-snRNP and anti-DNA antibodies." (PMID 27362648, 2016). "Conversely, as in the case of viral infections, we do not expect the SLC15A4-TASL complex to be involved in TLR7/9- and IRF5-independent autoinflammatory and autoimmune models, such as the lupus-like manifestations observed upon TREX1-deficiency which relies on the STING pathway." (PMID 39856058, 2025).
autoimmune disease (7 papers, 2018 to 2025). A disorder resulting from loss of function or tissue destruction of an organ or multiple organs, arising from humoral or cellular immune responses of the individual to their own tissue constituents. "Altogether, these data reveal the central role of the SLC15A4-TASL-IRF5 pathway for endosomal nucleic acid sensing by TLR7 and TLR9, and highlights the SLC15A4-TASL complex as as potential therapeutic target for autoimmune diseases associated with aberrant activation of these receptors, such as SLE." (PMID 39856058, 2025). "SLC15A4 also regulates mTOR-dependent inflammatory responses in B cells, and deficient SLC15A4 may contribute to the pathogenesis of autoimmune disease." (PMID 30069489, 2018). "Lastly, to assess the therapeutic potential of targeting the SLC15A4-TASL complex in autoimmune diseases, we investigated its relevance in a chemically-induced SLE model initiated by pristane (2,6,10,14-tetramethylpentadecane, TMDP) injection." (PMID 39856058, 2025). "Our findings provide insights into the molecular basis of regulatory switch involving a human solute carrier and offers an important framework for structure-guided drug discovery targeting SLC15A4-TASL-related human autoimmune diseases." (PMID 37863913, 2023). "Together with biochemical and cellular studies, our findings provide a structural basis for drug discovery targeting SLC15A4- or TASL-related human autoimmune diseases." (PMID 37863913, 2023). "More investigations have focused on SLC15A4 regulating TLR-triggered IRF7-IFN-I axis in autoimmune diseases." (PMID 34168674, 2021).
colitis (3 papers, 2022 to 2023). Inflammation of the colon. "SLC15A4/PHT1-deficient mice show alleviation of DSS-induced colitis." (PMID 36361959, 2022). "By being involved in multiple signaling pathways regulating cytokine production and thus innate immune responses, SLC15A4 has been shown to promote colitis in an in vivo mouse model." (PMID 35562597, 2022). "By being required for TLR9- as well as NOD1-mediated cytokine production, SLC15A4 has been shown to promote Th1-dependent colitis in vivo." (PMID 35562597, 2022). "Finally, SLC15A4/PHT1 protein is also a potential therapeutic target in patients with colitis." (PMID 36361959, 2022).
viral infection (3 papers, 2012 to 2025). "Next, we investigated the relevance of the SLC15A4-TASL pathway in the context of LCMV cl.13 viral infection, whose long term control critically depends on TLR7 and was reported to be compromised in feeble mice." (PMID 39856058, 2025). "Altogether, these data revealed that the SLC15A4-TASL axis is critical to control chronic viral infection and that the two TASL paralogues are functionally redundant to restrict LCMV in vivo, as only TASLDKO show persistent viral titre as in feeble mice." (PMID 39856058, 2025). "SLC15A4, selectively transcribed in bovine and also in human pDC, was shown to be required for signaling through TLR7 and TLR9 in murine pDC and, as a consequence, for pDC-mediated control of persistent viral infection." (PMID 30425716, 2018). "The critical role of SLC15A4-TASL pathway was not restricted to challenge with synthetic agonists, as it was pivotal to control chronic LCMV infection, a viral infection model whose clearance is highly dependent on TLR7, rather than RIG-I-MAVS antiviral response." (PMID 39856058, 2025).
colorectal cancer (2 papers, 2021 to 2022). A primary or metastatic malignant neoplasm that affects the colon or rectum. "For example, the mRNA level of SLC15A4 is increased in the majority of colorectal cancers, and the detection of SLC15A4 and CD44 in feces may help to identify initial CRC cells." (PMID 34168674, 2021).
glioblastoma (2 papers, 2021 to 2023). The most malignant astrocytic tumor (WHO grade IV). "The lack of effect of carnosine on SLC15A4 mRNA abundance was unexpected, since small interfering RNA (SiRNA)-mediated knockdown of both receptors (SLC15A3 and SLC15A4) was found to significantly reduce carnosine transport in human glioblastoma cells." (PMID 37171629, 2023).
inflammatory bowel disease (2 papers, 2015 to 2024). A spectrum of small and large bowel inflammatory diseases of unknown etiology. "PHT1 is hypothesised tomediate efflux of bacterial‐derived peptides into the cytosol perhaps in the colonwhere SLC15A4 mRNA expression is increased in inflammatory bowel disease." (PMID 26650446, 2015).
lung carcinoma (2 papers, 2021). "In lung cancer, SLC15A4, the analog of SLC15A2, was associated with survival and cell division regulation." (PMID 34977043, 2021). "SLC15A4 had the highest rate of deep deletion in the cohort, which was consistent with the decreased mRNA expression pattern in lung cancer patients." (PMID 34168674, 2021). "At the same time, we hope that our findings for SLC15A4 will provide new prospects for future research and clinical application in lung cancer patients." (PMID 34168674, 2021). "As the expression level of SLC15A4 is highly associated with its activity, the inhibitor or activator drugs of SLC15A4 are required to explore their functions in lung cancer, as well as the gene-editing tool." (PMID 34168674, 2021). "As other researchers have found that SLC15A4 may have a great impact on the mTOR pathway, the functions of SLC15A4 in the proliferation of lung cancer cells should also be revealed." (PMID 34168674, 2021). "For the expression between the lung cancer tissue and normal control tissue (n = 347), SLC15A3 and SLC15A4 were both decreased in lung adenocarcinoma (n = 483), and squamous cell carcinoma (n = 338)." (PMID 34168674, 2021). "However, for SLC15A4, there was no significant research meeting our selection criteria in the Oncomine database for lung cancer." (PMID 34168674, 2021).
prostate carcinoma (2 papers, 2001 to 2021). A carcinoma that arises from epithelial cells of the prostate gland. "In prostate cancer, SLC15A4 was highly expressed in certain prostate cancer cell lines." (PMID 34168674, 2021).
type 2 diabetes (2 papers, 2016 to 2025). "The first GWAS regarding SLC15A4 showed that it is closely associated with type 2 diabetes in Japan." (PMID 27362648, 2016).
ulcerative colitis (2 papers, 2022). An inflammatory bowel disease involving the mucosal surface of the large intestine and rectum. "Here, the first identification of SLC15A4/PHT1 gene products in human colonic epithelium of ulcerative colitis (UC) patients is reported, showing protein primarily localized in intracellular vesicle-like compartments." (PMID 36361959, 2022). "In light of studies that have linked SLC15A4/PHT1 to inflammatory diseases and IBD, here it has been investigated for the first time the expression of SLC15A4/PHT1 protein in colon histological sections of IBD patients with ulcerative colitis (UC), finding its major localization in epithelial cells." (PMID 36361959, 2022).
colorectal adenocarcinoma (1 paper, 2022). The most common type of colorectal carcinoma. "cBioPortal recorded six somatic missense mutations in the SLC15A4 gene (frequency = 1.01%) and only two somatic mutations in the PTGES gene (frequency = 0.34%) identified within 594 colorectal adenocarcinoma samples from the TCGA PanCancer Atlas." (PMID 35562597, 2022).
colorectal polyps (1 paper, 2022). "By being present in all four CRC-affected siblings as well as one direct descendant with colorectal polyps, the identified missense variant in SLC15A4 shows segregation with the disease and a potential for medium-to-high-penetrance susceptibility to CRC in the studied family." (PMID 35562597, 2022).
COVID-19 (1 paper, 2021). A disease caused by infection with severe acute respiratory syndrome coronavirus 2. "Other X-chromosomal genes may also be implicated in COVID-19, specifically Toll-Like Receptor 8 (TLR8) and TLR adaptor interacting with SLC15A4 on the lysosome (TASL)." (PMID 34858409, 2021).
Familial Cancer (1 paper, 2022). "After WES, we used our in-house developed Familial Cancer Variant Prioritization Pipeline and identified two novel variants in the solute carrier family 15 member 4 (SLC15A4) gene." (PMID 35562597, 2022).
glomerulonephritis (1 paper, 2021). A renal disorder characterized by damage in the glomeruli. "However, particularly in C57BL/6 mice, this model does not elicit strong renal pathology, and hence did not allow us to evaluate improvement of glomerulonephritis in the absence of SLC15A4." (PMID 33444326, 2021).